GDF15 (growth differentiation factor 15)
Diseases named in the same sentence as GDF15 in open-access papers (continued):
Sharing a sentence is not in itself a finding about the gene and the disease.
ureteral stone (1 paper, 2026). "This study investigated the diagnostic and predictive value of serum and urine GDF-15 in patients with acute renal colic due to ureteral stones." (PMID 41515626, 2026). "Overall, these results indicate that both serum and urinary GDF-15 levels are associated with the presence of ureteral stones, with urinary GDF-15 demonstrating superior diagnostic accuracy." (PMID 41515626, 2026). "This study was designed to investigate the diagnostic and predictive value of serum and urine GDF-15 levels in patients with acute renal colic due to ureteral stones." (PMID 41515626, 2026). "Our work is among the first to measure urine GDF-15 and associate it with ureterolithiasis, indicating a novel and practical application for this biomarker in clinical urology." (PMID 41515626, 2026). "ROC curve analysis was performed to evaluate the diagnostic performance of GDF-15 levels for identifying ureteral stones." (PMID 41515626, 2026). "Our study addresses this gap, showing that urine GDF-15 measurement could serve as a non-invasive, rapid diagnostic tool for detecting ureteral stones." (PMID 41515626, 2026). "In addition, it aims to evaluate the potential utility of GDF-15 in predicting the spontaneous passage of ureteral stones measuring 2–10 mm, and to assess its association with other predictive factors such as ureteral wall thickness, serum CRP, and hematological parameters." (PMID 41515626, 2026). "Collectively, these findings reinforce the interpretation that elevated GDF-15 in ureteral stone cases likely reflects the presence and severity of obstruction-induced renal insult." (PMID 41515626, 2026). "This study investigated the potential utility of serum and urine GDF-15 levels in diagnosing ureteral stones and predicting spontaneous stone passage in patients presenting with acute flank pain." (PMID 41515626, 2026). "Our observation that serum and urine GDF-15 levels were significantly higher in patients with ureteral stones compared to controls is supported by evidence from both experimental and clinical studies." (PMID 41515626, 2026). "In this context, elevated GDF-15 levels in patients with ureteral stones may represent a compensatory response to acute renal stress and inflammation rather than a stone-specific inflammatory signal." (PMID 41515626, 2026). "However, no studies to date have directly examined the relationship between GDF-15 levels and ureteral stone passage." (PMID 41515626, 2026). "Investigating the predictive potential of GDF-15 as a biomarker in this context could offer a novel perspective in the clinical management of ureteral stones." (PMID 41515626, 2026). "Studies on urine GDF-15 are scarce, and data on its use in diagnosing and differentiating acute obstructive uropathies such as ureteral stones are lacking." (PMID 41515626, 2026). "This study demonstrated that both serum and urine GDF-15 levels were significantly elevated in patients with radiologically confirmed ureteral stones compared with individuals without urinary tract pathology." (PMID 41515626, 2026). "Serum and urine GDF-15 levels were significantly higher in patients with radiologically confirmed ureteral stones (stone-positive, n = 41) compared to those without urinary tract pathology (stone-negative, n = 35) (both p < 0.001)." (PMID 41515626, 2026). "Our findings demonstrated that both serum and urine GDF-15 levels were significantly higher in individuals with ureteral stones compared to those without." (PMID 41515626, 2026).
vanishing white matter disease (1 paper, 2024). "Primarily, we used the murine model of vanishing white matter disease (VWMD), a neurological disease driven by persistent ISR in the CNS, to establish a link between levels of GDF15 in the cerebrospinal fluid (CSF) and ISR gene expression signature in the CNS." (PMID 38357857, 2024).
ventricular dilatation (1 paper, 2025). "In vivo, studies using GDF-15 analogs and antibodies against GFRAL to affect metabolic parameters and ventricular dilatation have shown potential for GDF-15-based therapeutic interventions." (PMID 39781722, 2025).
Vestibular schwannoma (1 paper, 2024). A vestibular schwannoma (also known as acoustic neuroma, acoustic neurinoma, or acoustic neurilemoma) is a benign, usually slow-growing tumor that develops from the VIIIth cranial nerve supplying the inner ear. "In addition to CCL2, the examination of our cell culture supernatants of VS primary cultures suggests that vestibular schwannoma cells produce the cytokines CCL5, CCL18, TGFB1, and GDF15, which has not yet been investigated for VSs." (PMID 39272860, 2024).
XFE progeroid syndrome (1 paper, 2024). A syndrome characterized by aged bird-like facies, lack of subcutaneous fat, dwarfism, cachexia and microcephaly. "Hence, it is unlikely that GDF15 plays an important role in preventing weight gain in patients with XFE progeroid syndrome." (PMID 38514641, 2024).
cancer (557 papers, 2005 to 2026). A tumor composed of atypical neoplastic, often pleomorphic cells that invade other tissues. "The reestablishment of GDF15 expression reverses stromal activation and restores epithelial characteristics in cancer cells, countering EMT-associated phenotypic changes." (PMID 41009692, 2025). "Given that Gdf15 and Fgf21 are both implicated in physiological outcomes associated with cancer treatment, these results provide an important foundational understanding of the biological pathways that initiate their expression." (PMID 39798881, 2025). "Elevated GDF15 expression is associated with poor prognosis and survival in multiple solid malignancies." (PMID 40354065, 2025). "This review aims to provide an overview of the role of GDF-15 in cancer cachexia, including the underlying neural mechanisms and their involvement in tumour immunity." (PMID 41294666, 2025). "High serum GDF15 levels are independently associated with poor cancer-specific survival, increased aggressiveness, and metastatic risk." (PMID 40868185, 2025). "In our cohort, GDF-15 was significantly associated with bleeding risk, even after rigorous adjustment for various clinical, cancer-specific, and laboratory parameters." (PMID 39967200, 2025). "The pathophysiological pathway linking abnormal GDF-15 secretion to involuntary weight loss and muscle wasting in patients with cancer has been elucidated, with elevated GDF-15 levels correlating with weight loss." (PMID 41294666, 2025). "In this narrative review, we aim to synthesize the current evidence on the biological function of GDF-15 in physiological and pathological states, and to examine its role as a diagnostic, prognostic, and predictive biomarker across cancer types." (PMID 40868185, 2025). "GDF‐15 plays a pivotal role in cancer cachexia‐associated muscle atrophy through multiple regulatory mechanisms." (PMID 40343378, 2025). "By integrating immunohistochemical analyses of tumor tissue with transcriptomic data from TCGA and GEO, we aimed to assess the diagnostic and prognostic potential of GDF15 in this type of cancer." (PMID 40725563, 2025). "Elevated GDF15 concentrations are associated with weight loss and poor outcomes in patients with various types of cancer." (PMID 40354065, 2025). "The aim of this study was to investigate the association and predictive ability of GDF-15 for bleeding risk in patients with cancer." (PMID 39967200, 2025). "Given its potential to differentiate between bleeding and thrombotic risk, a thorough investigation into the role of GDF-15 in predicting bleeding in cancer patients is warranted." (PMID 39967200, 2025). "GDF-15-targeted therapy represents a novel approach for addressing neural mechanisms in cancer-associated symptoms and therapeutic implementation." (PMID 41294666, 2025). "The altered expression of GDF15 is associated with many cancers due to the inflammation caused by the disease." (PMID 40128491, 2025). "Mouse models neutralising GDF‐15 or IL‐6 have confirmed the amelioration of muscle loss and therefore the potential for prolonged cancer survival." (PMID 41380167, 2025). "Targeting GDF-15 plays a crucial part in anorexic patients by preventing weight loss caused by cancers." (PMID 39781722, 2025). "A significant association of elevated GDF15 levels with poor cancer prognosis is suggestive of its pro-tumorigenic nature." (PMID 40144214, 2025). "High expression of GDF15 in various cancer types is associated with tumor invasiveness and poor prognosis." (PMID 40190762, 2025). "We found that in systemic circulation, pre-Cx cancer progression was associated with moderate increases in IL-6 and GDF15 concentrations, dramatic induction of positive-APP production and marked reductions in the levels of most amino acids." (PMID 40124481, 2025).
cancer (continued). "In a phase II study of patients with advanced cancer, elevated serum GDF15, and cachexia, the GDF15 inhibitor ponsegromab was associated with a median weight gain of approximately 2.81 kg compared with placebo at 12 weeks." (PMID 40354065, 2025). "In the cancer population, the association between GDF-15 and overall survival has also been well documented, with reports spanning a wide variety of tumor subtypes, stages, and treatment settings." (PMID 39967200, 2025). "The dysregulation of GDF-15 expression and signaling pathways is associated with diverse human diseases and cancer progression." (PMID 39728572, 2024). "Researchers have linked growth differentiation factor-15 (GDF-15) to a variety of conditions such as cardiovascular disease, inflammation, cancer, and kidney disease, and have reported hepcidin as a biomarker for iron regulation in ACD." (PMID 38883134, 2024). "Specifically, it assesses the association of GDF-15 with cancer-related cachexia and its potential role as a prognostic marker." (PMID 39766045, 2024). "GDF15 is a well-established hallmark of solid cancer tumors of various origins and can be targeted for cancer therapy." (PMID 38892145, 2024). "Although cancer cachexia is associated with GDF15 overexpression, GDF15 itself holds biological significance." (PMID 39172988, 2024). "Recent research has been focused on GDF15, a circulating growth factor associated with several types of cancer including prostate, gastric, colon, pancreas, and breast." (PMID 39697630, 2024). "GDF15 has the potential to serve as a biomarker for cancer-related weight loss and a therapeutic target." (PMID 39172988, 2024). "Elevated serum levels of GDF‐15 are reported in patients with various types of cancer and are associated with weight loss and poor survival." (PMID 38500292, 2024). "Many studies have associated GDF15 with a plethora of age-related diseases, such as neurodegenerative diseases, cardiovascular diseases, metabolic diseases and cancer." (PMID 38808117, 2024). "More generally, GDF15 expression is induced in response to cellular stress, which explains why it is frequently associated with many diseases including cancer, obesity, cachexia, cardiovascular events, kidney diseases, etc.." (PMID 38892145, 2024). "For instance, cancer-associated fibroblasts (CAF) are a rich source of GDF15 and they promote the creation of an immunosuppressive microenvironment in prostate cancer." (PMID 39643709, 2024). "Select genes that were found to be associated with chemoresistance in other cancers included GDF15, THBS1, CDKN1A and CLU." (PMID 38673926, 2024). "The unique exception is represented by growth differentiation factor 15 (GDF15), a member of the transforming growth factor-beta superfamily, implicated in mitochondrial dysfunction, cancer growth, and epithelial-to-mesenchymal transition." (PMID 37762344, 2023). "Factors secreted by muscles, such as myostatin and GDF15, or factors secreted by cancer-associated immune cells initiate a series of processes that cause cancer cachexia." (PMID 37217930, 2023). "GDF15 has been found to be a key driver of cachexia syndrome, significant body weight loss that often occurs in chronic diseases including cancer or in case of drug-induced organ injury." (PMID 37495707, 2023). "Anticancer drugs used in chemotherapy can cause cellular stress and death leading to drastic GDF15 induction in both cancer and host cells." (PMID 37495707, 2023). "Clinically, IL-1β, IL-18, IL-6, and MIC-1/GDF-15 levels are associated with the risk of carcinoma and the prognosis of established cancer." (PMID 37715239, 2023). "Abnormally increased GDF‐15 levels in the circulation of cachectic cancer patients and rodents have been negatively associated with disease outcome and death." (PMID 37654192, 2023). "In disease such as cancer, GDF15 levels can be elevated up to 100-fold, thereby causing pathological conditions." (PMID 37495707, 2023).
cancer (continued). "In various cancers, higher GDF-15 levels were associated with worse disease-free and overall survival." (PMID 37106424, 2023). "Intense exercise, for example, can lead to great GDF15 release from skeletal muscle but also smoking, increasing age, injury, inflammation and many diseases (notably cancers) are associated with higher GDF15 levels in serum." (PMID 36642986, 2023). "To summarize, our results revealed that anticancer drugs differentially induce GDF15 expression in cancer cell lines depending on the drug and the cell line’s mutational and gene expression profile." (PMID 37495707, 2023). "GDF15, a stress-induced cytokine, is known to have immunomodulatory functions and its high expression is often associated with cancer progression." (PMID 35853851, 2022). "Most studies examining the role of GDFs in cancer have centered on GDF15 because of its being implicated in acute and chronic inflammatory diseases." (PMID 36353620, 2022). "The important role GDF-15 plays in cancer is illustrated further by the association of gene variants of the cytokine with cancer risk, prognosis, and mortality." (PMID 36361969, 2022). "Elevation in circulating GDF15 correlates with cancer cachexia and GDF15-induced weight loss in mice was reported to be mainly mediated by a GDNF family receptor alpha like (GFRAL)-Ret proto-oncogene (RET) signaling complex in brainstem neurons." (PMID 35379793, 2022). "Higher GDF15 levels have also been associated with all-cause mortality as well as mortality associated with heart failure and acute myocardial infarction, cancer, advanced heart failure, and end-stage chronic kidney disease." (PMID 35916366, 2022). "It has also been reported that GDF-15 is associated with side effects from platinum-based cancer therapy, suggesting a close connection between senescence and cancer therapy-related metabolism." (PMID 34667277, 2022). "GDF15 was previously associated with increased migration of cancer cells and endothelial cells, but to date, there is no existing evidence of its direct impact on fibroblast migration." (PMID 35993367, 2022). "Increased GDF-15 expression has been also associated with many cancers affecting the mammary gland, colon, pancreas and prostate." (PMID 35159548, 2022). "It has also been reported that GDF-15 plasma level is associated with the severity of side effects in cancer patients following platinum/ cisplatin-based chemotherapy." (PMID 35778385, 2022). "In cancer, GDF15 mediates cachexia, causing extreme weight loss and muscle wastage in late-stage cancer patients." (PMID 35626166, 2022). "Elevated GDF15 levels are linked to various pathological conditions, including inflammation, cardiovascular disease, cancer, obesity, and kidney disease." (PMID 35160195, 2022). "The relationship between GDF-15 and outcomes was also supported in the groups of high BMI, with a consistently increasing risk of all-cause and cancer death (except CV death) with elevated GDF-15 levels." (PMID 34150865, 2021). "GDF15 is highly associated with malignant human cancers and it has been suggested that it is involved in tumor angiogenesis." (PMID 34445593, 2021). "This study further found that high GDF-15 levels in patients with low BMI conferred an increased risk for all-cause death, cancer death, and CV death." (PMID 34150865, 2021). "For example, the catabolic effect of GDF15 has been linked to cancer cachexia, and inhibition of GDF15 activity by targeting its receptor was shown to reverse cancer cachexia in mice." (PMID 33464381, 2021). "In the sub-analyses stratified the range of BMI, elevated GDF-15 levels were associated with increased risks of all-cause and cancer death in the groups of low and high BMI." (PMID 34150865, 2021). "High circulating levels of GDF15 are associated with weight loss and shorter survival in cancer patients." (PMID 33925872, 2021).